IL4 (interleukin 4)
Diseases named in the same sentence as IL4 in open-access papers (continued):
Sharing a sentence is not in itself a finding about the gene and the disease.
atopic dermatitis (continued). "Interestingly, elevated IL-4, a key T-helper 2 (Th2) cytokine implicated in intrinsic atopic dermatitis, has been found in non-lesional skin in EGFRi responsive patients who developed an acneiform eruption." (PMID 39583056, 2024). "(2016) reported that IL‐13 may play an important role in the formation of atopic response, compared to IL‐4 in dogs with atopic dermatitis, in the present study, it was shown that both IL‐4 and IL‐13 cytokine responses to environmental allergens occur in dogs with atopic dermatitis." (PMID 38648253, 2024). "Gelato and Mastorino, in their analysis of a patient who developed multiple sclerosis (MS) after starting dupilumab treatment for atopic dermatitis, hypothesized that dupilumab could induce a shift toward Th1/Th17 polarization by blocking the shared receptor subunit for IL-4 and IL-13." (PMID 39007153, 2024). "Our study may reveal additional pathways through which IL-4 is involved in atopic dermatitis." (PMID 38357652, 2024). "Finally, IL-4 and 13 accounted for 11.7% of trials, especially for atopic dermatitis." (PMID 35529441, 2022). "Moreover, IL-4 is known to inhibit the synthesis of caspase-14, which might contribute to barrier disruption in atopic dermatitis." (PMID 36362566, 2022). "Similarly, the probiotic function of L. plantarum IS-10506, a probiotic strain isolated from the Indonesian fermented milk product dadih, could downregulate IL-4 in children with mild atopic dermatitis." (PMID 33828554, 2021). "Besides, the lysates of L. plantarum could inhibit IL-4 level in Nc/Nga mice and regulate inflammatory diseases like atopic dermatitis." (PMID 33828554, 2021). "However, this activity could have a harmful effect on patients with atopic dermatitis since the excessive expression of IL-4 induces allergic reactions." (PMID 34572971, 2021). "Moreover, inhalation of air pollutants via the pulmonary system could overactivate the expression of IL-4, contributing to the development of atopic eczema." (PMID 31937319, 2020). "In allergic dermatitis models, neutrophils exacerbate inflammation via LTB4‐mediated CD4+ T cell recruitment and IL‐4/IL‐13 upregulation." (PMID 41583119, 2026). "The atopic dermatitis cell model was established by co-stimulating with TNF-α (10 ng/mL) and IL-4 for 48 h." (PMID 41556698, 2026). "Specifically, the cytokines that promote isotype switching (e.g., IL-4, IL-13, and IFN-γ) are only poorly to modestly expressed in necrobiotic skin when compared with other inflammatory conditions like atopic dermatitis." (PMID 39989459, 2025). "Cell-intrinsic deregulation of the TGF-β pathway promotes the IL-4/IL-4Rα/GATA3 axis, supporting atopic phenotypes in humans, including atopic dermatitis." (PMID 39859044, 2025). "IL23A, IL4, IL13, and TNFR1 are targets of medically efficacious drugs in widespread use in psoriasis and atopic dermatitis, consistent with the observed enhanced likelihood of success for polygenic disease therapeutics directed at GWAS-linked targets." (PMID 40998781, 2025). "In keratinocytes, BCP specifically counteracts Th2-driven inflammation by suppressing the IL-4/IL-13–MAPK–early growth response 1 (EGR1) axis, which otherwise promotes thymic stromal lymphopoietin (TSLP), a central epithelial alarmin in atopic dermatitis." (PMID 41304852, 2025). "The graph of Network Pharmacology Survey shows that the effect of silica and silver nanoparticles on the expression of various genes such as IL4, IL6, IL8 and TNFα leads to the occurrence of various skin diseases such as atopic dermatitis." (PMID 38454025, 2024). "The objective of this review was to evaluate the efficacy of IL-4/IL-13 inhibitors and JAK inhibitors concerning the restoration of skin barrier abnormalities in atopic dermatitis." (PMID 39202657, 2024). "In conclusion, this study underscores the efficacy of IL-4/IL-13 inhibitors and JAK inhibitors in improving skin barrier function in atopic dermatitis patients." (PMID 39202657, 2024).
atopic dermatitis (continued). "Materials and Methods: A comprehensive review of the literature was conducted, focusing on studies that assess the use of IL-4/IL-13 inhibitors and JAK inhibitors for atopic dermatitis." (PMID 39202657, 2024). "This review mainly summarizes the beneficial effects of IL-4/IL-13 inhibitors, and comparatively less of JAK inhibitors, on skin barrier function in atopic dermatitis." (PMID 39202657, 2024). "This systematic review aims to evaluate the restoration of skin barrier abnormalities with interleukin-4/interleukin-13 (IL-4/IL-13) inhibitors and Janus kinase (JAK) inhibitors in atopic dermatitis." (PMID 39202657, 2024). "Modulation of immune system by inhibition of IgE serum levels and cutaneous edema.Reduction of IL-4, IFN-γ, and TNF-α production.Decrease of lymph node size in atopic dermatitis mouse." (PMID 37685100, 2023). "High immunoexpression of INF-γ was noted by immunohistochemistry (IHC) in inflamed regions of tissues of 12 vulvar LS while increased levels of INF-γ, IL-4, TNF-α and IL-10 were observed in atopic dermatitis." (PMID 35103930, 2022). "The levels of IL-4, IFN-γ, and IL-6 significantly increase in the dorsal skin of animals with inflammatory diseases such as atopic dermatitis." (PMID 35222003, 2021). "It is worth mentioning that previous studies showed that RA inhibited the IL-4 and IFN-γ expression activated CD4+ T cells and de-creased immune cell infiltration in atopic dermatitis skin lesions in mice." (PMID 33986690, 2021). "A recent study observed that MIF amounts were increased in the allergen-induced skin tissue of atopic dermatitis murine models, and the elevated MIF levels promoted the secretion of IL-4 and IL-5, and eosinophil recruitment in the skin." (PMID 34305594, 2021). "T-helper type 2 (Th2) cytokines (such as IL-4, IL-5, IL-13 and IL-31), but also T-helper type 1(Th1) cytokines (such as IFN-γ and TNF-α) are overproduced in allergic dermatitis in humans and play an important role in the pathogenesis of this disease." (PMID 34577127, 2021). "In this article, we analyzed IL-4 production from PBMC of allergic horses with CH, an IgE-mediated seasonal allergic dermatitis that is induced by allergens from Cul midges." (PMID 34038479, 2021). "Second, for the treatment of atopic dermatitis, C. asiatica significantly reduced the inflammation response (TNF-α ↓, IL-1β ↓, IL-8 ↓, IL-4 ↓, and IL-13 ↓), and also the local immune response (IgE ↓)." (PMID 33013406, 2020). "Patients on immunosuppressive therapy for severe atopic dermatitis should be strictly monitored or transitioned to safer anti-IL4/IL13 immune-modulatory agents, as advocated by the European Task Force on atopic dermatitis." (PMID 32566128, 2020). "The reason for this phenomenon seems to be that the previously reported anti-allergic effect such as inhibiting IL-4 and CD4+ of SCRT and its ingredients affected the progression and remission of atopic dermatitis." (PMID 33324225, 2020). "Especially, antibodies against IL-4 and IL13 have been investigated as molecular targets for moderate-to-severe atopic dermatitis." (PMID 32375285, 2020). "Maltol most potently inhibited IL-4 levels in RBL-2H3 cells and suppressed the development of atopic dermatitis-like symptoms in our DNCB-induced mouse model of AD." (PMID 35516135, 2019). "Ta-EE suppressed the mRNA expression of T helper 2-specific cytokines, IL-4 and IL-5, and the proinflammatory cytokine IFN-γ in the atopic dermatitis skin lesions of AD mice." (PMID 29736153, 2018). "It was previously shown that level of IL-4 was increased in the serum of allergic rhinitis and allergic children, and TSLP were significantly increased in the serum of atopic dermatitis children." (PMID 27445435, 2016).
atopic dermatitis (continued). "IL4 and IL4RA are candidate genes for atopic diseases, i.e., diseases that are clinically expressed as atopic asthma, allergic rhinitis, and atopic dermatitis or that can be defined by at least one positive specific IgE response to inhalant or food allergens." (PMID 25238536, 2014). "It has been shown that patients with atopic dermatitis, a TH2- driven disease, have significantly greater peripheral blood eosinophil apoptosis in response to IL-4." (PMID 24971469, 2014). "Inflammatory mediators such as the Th2 cell–derived cytokines IL-4 and IL-31 and TNF-α have been shown to impair epidermal differentiation and have been suggested to play important roles in the pathogenesis of atopic dermatitis." (PMID 23157658, 2013). "For example, in atopic dermatitis, combining a JAK inhibitor with dupilumab (an IL‐4/IL‐13 inhibitor) may enhance disease control while reducing the dosage requirements of each agent, thereby minimizing adverse effects." (PMID 40536117, 2025). "Atopic dermatitis (AD) is known to increase the expression levels of SOCS3 and IL-4." (PMID 40005151, 2025). "Additionally, a decrease in IL-4 levels and an increase in IFN-γ levels were observed in 5 out of 8 treated dogs, corroborating our previous findings from an allergic dermatitis mouse model." (PMID 41227429, 2025). "In addition, the gene expression levels of IL-4, IL-13, CXCL10, CCL5, CCL17, and CCL22, which are related to atopic dermatitis, were significantly decreased by HCFE in DPM-stimulated HaCaT cells." (PMID 39599592, 2024). "By contrast, atopic dermatitis and Th2-related genes, including Il4, Il5, Il13 and Il31 were lowly expressed or not detected at all, and other atopic dermatitis-related transcripts (Ccr4, Ccl17, Ccl24) were not significantly differentially expressed." (PMID 38528069, 2024). "The topical application significantly reduced dermatitis scores, mast cell infiltration, and serum levels of immunoglobulin E (IgE), IFN-γ, interleukin (IL)-4, IL-17, and thymic stromal lymphopoietin (TSLP), demonstrating its effectiveness in treating atopic dermatitis (AD)." (PMID 38790668, 2024). "In addition, the expression of IL-4, IL-13, CXCL10, CCL5, CCL17, and CCL22, which are atopic dermatitis mediators, increased 2- or 3-fold in HaCaT cells treated with DPM compared with that in the control group." (PMID 39599592, 2024). "(2014) reported a significant increase in IL‐4 concentrations in dogs with atopic dermatitis, while no change in IL‐6 and IL‐10." (PMID 38648253, 2024). "Considering all the results in the experimental model and in dogs spontaneously affected with atopic dermatitis, some similarities have been shown for TH2 cytokines with a significant increase of IL-4 and IL-13 in sensitized and lesional sites compared with control sites." (PMID 39852879, 2024). "According to data from a murine model of atopic dermatitis, IL-17 is instrumental in transforming naive T cells into Th2 cells while concurrently diminishing Th2 chemokine expression and populations of IL-4-producing cells in the absence of IL-17A47." (PMID 38418932, 2024). "(2016) reported that IL‐13 concentrations were significantly increased in dogs with atopic dermatitis, while IL‐4 did not change." (PMID 38648253, 2024). "Our analysis showed that the IL-4 and IL-13 Reactome pathway was significantly enriched in HS lesional skin compared with HS non-lesional skin, atopic dermatitis, and psoriatic skin." (PMID 38069342, 2023). "As in atopic dermatitis epidermis, we found no obvious redistribution of E-cadherin throughout the IL-4/IL-13-treated skin." (PMID 37289055, 2023). "We identified a novel heterozygous germline mutation STAT6 c.1255G > C, p.D419H leading to overactivity of IL-4 JAK/STAT signalling pathway, in a kindred affected by early-onset atopic dermatitis, food allergy, eosinophilic asthma, anaphylaxis and follicular lymphoma." (PMID 37316763, 2023).
atopic dermatitis (continued). "As IL-4/IL-13 treatment of epidermal equivalents based on N/TERT-1 cells can induce histopathological and molecular hallmarks of atopic dermatitis, we investigated whether the cytokine-induced barrier alterations enhance HSV-1 invasion." (PMID 37289055, 2023). "The pathogenesis of atopic dermatitis involves various inflammatory cytokines, particularly IL-4 and IL-13, acting on both immune cells and nonimmune cells and enhancing type 2 inflammation." (PMID 37298299, 2023). "In NC/Nga mice with atopic dermatitis, the expression of Il4 did not change between the vehicle- and calcitriol-treated groups." (PMID 37298299, 2023). "Nectin-1 showed no major redistribution in the thickened atopic dermatitis and IL-4/IL-13-treated human epidermis in which HSV-1 can invade." (PMID 37289055, 2023). "The roles of IL-4, IL-13, IL-31, and TSLP in the pathogenesis of atopic dermatitis might involve a dysfunctional epidermal barrier and allergen sensitization, which are characterized by intense itching and pruritus." (PMID 37676892, 2023). "Experimental model of food allergy in mice demonstrated that epicutaneous sensitization to OVA or peanut through an atopic dermatitis-like skin led to TSLP-dependent infiltration of basophils to the skin and basophil-derived IL-4 production that induce enhanced Th2 response in the skin." (PMID 36904070, 2023). "Another animal study found that EA increased the serum levels of interferon-γ of mice with atopic dermatitis, with no significant change in IL-4 levels (the acupoints are “Quchi” (LI11) and “Neiguan” (PC6))." (PMID 37675019, 2022). "Tumor necrosis factor-α (TNF-α), interleukin-17 (IL-17), interleukin-6 (IL-6), interleukin-4 (IL-4) antibodies and other drugs have been proven useful in treating rheumatoid arthritis (RA), psoriasis, cytokine release syndrome (CRS), atopic dermatitis (AD) and other autoimmune diseases." (PMID 35844550, 2022). "In a 12-week-long randomized, double-blind and placebo-controlled study performed in children aged one and twelve years, the use of L. plantarum CJLP133 strain reduced IFN-γ, eosinophil and IL-4 levels, and thus the AD scores such as SCORAD (SCORing Atopic Dermatitis)." (PMID 33921772, 2021). "In animals, a study found that electroacupuncture promoted the secretion of IFN-γ in the serum of mice with atopic dermatitis, while there was no sensible change about IL-4." (PMID 35431769, 2021). "Lastly, medically targeted cytokines known to drive inflammatory skin diseases such as psoriasis (IL-17, IL-22, and IL-23) and atopic dermatitis (IL-4, IL-5, IL-13) were not identified in healthy skin." (PMID 33154365, 2020). "Smits and colleagues established psoriasis and atopic dermatitis models using N/TERT epidermal skin by adding Th1/Th17 (TNF-α, IL-6, IL-1α, IL-17, and IL-22) cytokines and Th2 (IL-4 and IL-13) cytokines, respectively, during the final stage of the skin maturation." (PMID 32509598, 2020). "In addition, Ta-EE suppressed the expression of T helper 2-specific cytokines, such as IL-4 and IL-5 and proinflammatory cytokines, such as IFN-γ and IL-12 in a transcriptional level in the atopic dermatitis skin lesions of the AD mice and total splenocytes." (PMID 29736153, 2018). "Taken together, epidermal over expression of IL-4 results in minor inflammation characterized by increased inflammatory cytokine expression and infiltration of CD3+ lymphocytes in the skin before the onset of an atopic dermatitis-like skin disease." (PMID 26752054, 2016). "Overexpression of IL-4 and IL-13 in the skin seems not to be sufficient for the induction of a fully developed atopic dermatitis phenotype." (PMID 23531535, 2013). "Analysis by immunohistochemistry of airway mucosa of people with atopic asthma after antigen challenge revealed that large numbers of CCR4+ and CCR8+ T cells express IL-4, and CCR4 expression was prominent in people with severe atopic dermatitis, which decreased upon abatement of disease activity." (PMID 15526056, 2004).
atopic dermatitis (continued). "The immunomodulatory effects of probiotics can reduce the severity of atopic dermatitis by inhibiting Th2 cell responses, cytokines such as IL-4, IL-5, IL-6, and IL-13 are no longer secreted, INF-γ (cytokines released by Th1 cells) is decreased, phagocytosis is stimulated, and serum IgA increases." (PMID 39781533, 2025). "In conclusion, using mice and ovalbumin mimicking allergic dermatitis and using IBH, a natural equine skin allergic disease, we demonstrated that IL‐5 vaccination significantly decreased allergen‐specific IgE levels, together with Th1/Th2 cytokines, such as IL‐4 and IFNγ." (PMID 40838325, 2025). "Aside from filaggrin, loricrin and involucrin are also downregulated by IL-4 and IL-13 in lesional and non-lesional atopic dermatitis skin, contributing to a defective skin barrier that allows penetration of bacteria and allergens into the skin, leading to infections and allergen sensitization." (PMID 39202657, 2024). "Additionally, there were significantly more IL-4+ T-cells, in cats with allergic dermatitis compared to non-pruritic control cats." (PMID 39911485, 2024). "Sleep disturbances in atopic dermatitis are not only due to sleep deprivation related to nighttime itching but also to dysregulation in the release of inflammatory mediators (IL-1b, IL-2, TNF-a, IFN-g, IL-6, IL-4, and IL-10) and neuroendocrine molecules such as cortisol and melatonin." (PMID 38731996, 2024). "The presence of low levels of Il4 but no detectable Il17 or IL22 suggest that the lesions in our mice may represent a model of atopic dermatitis." (PMID 34445339, 2021). "Besides, L. plantarum IS-10506 could regulate the immune system by decreasing IL-17, IL-4, and interferon (IFN)-γ levels in serum of children with atopic dermatitis." (PMID 33828554, 2021). "Given increased levels of type 2 cytokines, IL-13, IL-4 and IL-5, in acute atopic eczema lesions and enhanced production of epithelial cytokines IL-33, IL-25 and TSLP, it is plausible that group 2 innate lymphoid cells contribute to the pathogenesis of atopic dermatitis." (PMID 25427661, 2014). "Additionally, we examined the effects of ALBE on the expression and secretion of Th2 cytokines, such as IL-4 and IL-5, in primary murine splenocytes using RT-PCR and ELISA assays to investigate the further involvement of ALBE in Th2 functions in the atopic dermatitis-like skin lesions." (PMID 21303540, 2011).